NSUN2 (NOP2/Sun RNA methyltransferase 2)
Diseases named in the same sentence as NSUN2 in open-access papers (continued):
Sharing a sentence is not in itself a finding about the gene and the disease.
microcephaly (17 papers, 2013 to 2026). A congenital or acquired developmental disorder in which the circumference of the head is smaller than normal for the person's age and sex. "Some Gulf War Veterans report loss of olfaction and this is often a prodromal sign of neurodegeneration, Nsun2 is a methyltransferase and is associated with Dubowitz syndrome, an autosomal recessive disease that produces intellectual delay and microcephaly." (PMID 40606660, 2025). "The clinical presentation of these subjects with NSUN2 deficiency includes facial dysmorphism, microcephaly, short stature, ID, growth restriction, language impairment, hypotonia and delayed puberty." (PMID 38643142, 2024). "Although some clinical manifestations were highly variable, the core phenotypes associated with NSUN2 mutations were dysmorphic facies, microcephaly, short stature, ID, growth restriction, language impairment, hypotonia and delayed puberty." (PMID 38643142, 2024). "This idea was further bolstered by a report about another methyltransferase (NSUN2), which is implicated in microcephaly and associated with decreased translation of mRNAs into protein." (PMID 39251572, 2024). "In summary, we uncovered a novel, homozygous, pathogenic variant in NSUN2 in two Chinese patients, from the same family, with moderate ID, dysmorphic facies, microcephaly, short stature, DD, language impairment and other congenital abnormalities." (PMID 38643142, 2024). "NSUN2 is essential for brain development and loss-of-function mutations in the NSUN2 gene cause neurodevelopmental disorders including microcephaly, motor deficits and growth retardation in humans and mice." (PMID 33525475, 2021). "Loss of function of the NSun2 gene impairs brain development during early embryo formation stage and causes microcephaly in mouse and human." (PMID 33093178, 2020). "Loss-of-function mutations in the NSUN2 gene in both mouse and human cause growth retardation and neurodevelopmental deficits including microcephaly, as well as defects in cognition and motor function." (PMID 28041877, 2017). "Recently, a syndrome of mental retardation, microcephaly and short stature was described, caused by mutations in NSUN2, encoding a methyltransferase that catalyzes the intron-dependent formation of 5-methylcytosine at C34 of tRNA-leu(CAA)." (PMID 24204302, 2013). "Interestingly, ANG inhibition rescues loss of NSUN2 mediated cellular stress and microcephaly in mice, and thus has therapeutic potential to treat neurodevelopmental disorders." (PMID 33525475, 2021). "Failure to produce NSUN2 protein during development reduces the sensitivity toward growth factors and decreases the number of upper-layer neurons, and causes neurodevelopment deficits including microcephaly." (PMID 28041877, 2017). "Loss-of-function mutations in the cytosine-5 RNA methylase NSUN2 cause neurodevelopmental disorders in humans, yet the underlying cellular processes leading to the symptoms that include microcephaly remain unclear." (PMID 28041877, 2017). "Similarly, mutations in human NSUN2, which is required for m5C modification of body residues 48, 49, and 50 in mammals, as well as C34 of the anticodon, cause variable phenotypes that include microcephaly as a feature." (PMID 26416026, 2015).
cervical cancer (16 papers, 2014 to 2026). A primary or metastatic malignant neoplasm involving the cervix. "A previous study showed the potential biological function of NSUN2, a regulator of m5C, in common gynaecological cancers, where NSUN2 promotes cervical cancer cell migration and invasion by causing m5C methylation of keratin 13 (KRT13) transcripts." (PMID 37042849, 2023). "In cervical cancer, NSUN2 promotes m5C modification on KRT13, and m5C-methylated KRT13 is recognized and stabilized by the m5C reader protein YBX1." (PMID 41462962, 2025). "The m5C regulator NSUN2 promoted cervical cancer cell migration and invasion by inducing m5C methylation of keratin 13 (KRT13) transcripts." (PMID 38655053, 2024). "In cervical cancer patients, NSUN2 and YBX1, which catalyze and recognize methylation sites, respectively, induce KRT13 mRNA methylation and translational activation." (PMID 37325635, 2023). "To investigate the biological function of highly expressed NSUN2 in cervical cancer, we then established NSUN2 knockdown stable clones in two common cervical cancer cell lines CaSki and SiHa." (PMID 35280737, 2022). "CCK-8 and real-time cell analysis (RTCA) assays showed that knockdown of NSUN2 has little effect on cervical cancer cell proliferation, and downregulation of NSUN2 led to minor changes in cell cycle distribution." (PMID 35280737, 2022). "In this study, we not only demonstrated the ability of KRT13 to stimulate cervical cancer cell migration and invasion, but also revealed a novel upstream NSUN2-m5C-YBX1 pathway for regulation of KRT13 mRNA stability and expression." (PMID 35280737, 2022). "In contrast, NSUN2 played a robust role for tumorigenesis in cervical cancer via promoting m5C modification on KRT13 transcripts, which were then recognized and stabilized by an m5C reader protein YBX1." (PMID 35280737, 2022). "In this study, we investigated the potential biological functions of NSUN2 in common gynecologic cancers including cervical cancer, ovarian cancer, and endometrial cancer." (PMID 35280737, 2022). "Collectively, our results demonstrated that NSUN2 promotes cervical cancer cell migration and invasion via a KRT13-dependent manner." (PMID 35280737, 2022). "We next collected 29 normal cervix and 30 cervical cancer paraffin sections to prepare tissue chip, and the immunohistochemistry analysis showed higher levels of NSUN2 in cervical cancer than in normal tissues." (PMID 35280737, 2022). "We identified keratin 13 (KRT13) mRNA as the downstream target gene of NSUN2 in cervical cancer, which contributes to the activity of tumor cell migration and invasion." (PMID 35280737, 2022). "Bioinformatics analysis showed that NSUN2 was upregulated and negatively related to overall survival in cervical cancer." (PMID 35280737, 2022). "Notably, NSUN2 deletion in cervical cancer also significantly inhibited cancer cell migration and invasion." (PMID 38572667, 2024). "As a whole, our findings not only demonstrated distinct roles of NSUN2 in different gynecological cancers, which represented the nature of diversity and complexity of human malignancies, but also discovered a novel NSUN2-dependent m5C-YBX1-KRT13 oncogenic regulatory pathway in cervical cancer." (PMID 35280737, 2022). "Furthermore, besides mRNA levels, the expression of KRT13 protein was also obviously downregulated in NSUN2 knockdown CaSki and SiHa cells, suggesting KRT13 mRNA as the downstream target gene of NSUN2-m5C regulatory pathway in cervical cancer cells." (PMID 35280737, 2022). "In line with this, we found that NSUN2 mRNA level was significantly upregulated in cervical cancer tissues (n = 20) compared to normal cervix samples (n = 20), and NSUN2 protein levels were also higher in randomly selected tumor tissues (n = 5) than their paired adjacent normal tissues." (PMID 35280737, 2022). "In other words, NSUN2 promoted cervical cancer migration and invasion in an m5C-dependent manner." (PMID 35280737, 2022).
cervical cancer (continued). "On the contrary, NSUN2 played a role in tumorigenesis of cervical cancer; depletion of upregulated NSUN2 notably inhibited migration and invasion of cancer cells, and only wild-type but not catalytically inactive NSUN2 rescued these malignant phenotypes of cancer cells." (PMID 35280737, 2022). "In cervical cancer, the RNA methyltransferase NOL1/NOP2/Sun domain family member 2 (NSUN2) stabilizes LRRC8A mRNA through m5C modification, activating the PI3K-AKT signaling pathway, which ultimately suppresses cell apoptosis and facilitates tumorigenesis." (PMID 41439137, 2026). "Mechanistically, YBX1 recognises NSUN2‐induced m5C methylation of keratin 13 (KRT13) transcripts, enabling its stable expression and ultimately promoting cervical cancer survivability." (PMID 38572667, 2024). "Next, we verified expression of these genes in the other cervical cancer cell line, SiHa, and found that only KRT13 levels displayed significant downregulation in NSUN2-depleted SiHa cells as well." (PMID 35280737, 2022). "In cervical cancer, destabilizing LRRC8A mRNA through NSUN2 inhibition or directly antagonizing LRRC8A function could reactivate apoptotic pathways." (PMID 41439137, 2026). "Taken together, these findings suggest that NSUN2 likely contributes to the carcinogenesis of ovarian cancer and cervical cancer but not endometrial cancer." (PMID 35280737, 2022). "Although NSUN2 is the main methyltransferase for m5C methylation on mRNA, we extended to explore the expression of all potential m5C methyltransferases (NOP2, NSUN3, 4, 5, 6, 7, and DNMT2) in cervical cancer, ovarian cancer, and endometrial cancer." (PMID 35280737, 2022). "We studied NSUN2 and METTL1, the human orthologs of Trm4 and Trm8 in yeast, and demonstrated that these RTD-related tRNA modifying enzymes are involved in 5-FU sensitivity in cervical cancer HeLa cells." (PMID 25233213, 2014). "Although NSUN2 levels were upregulated in both ovarian and cervical cancers, knockdown of NSUN2 did not reduce aggressive phenotypes of ovarian cancer cells, suggesting that upregulation of NSUN2 is likely an accompanied effect but not a fundamental driving force in ovarian cancer." (PMID 35280737, 2022). "However, in our previous studies, NSUN2 expression was not altered during the cell cycle of HeLa cervix carcinoma cells." (PMID 25233213, 2014).
prostate carcinoma (15 papers, 2019 to 2025). A carcinoma that arises from epithelial cells of the prostate gland. "Our study revealed for the first time that NSUN2 is highly expressed in prostate cancer and is strongly associated with tumor stage, lymph node invasion, Gleason score, and biochemical recurrence." (PMID 35978830, 2022). "we found that NSUN2 was closely implicated in the prognosis of prostate cancer, then verified the expression of NSUN2 in clinical samples, and obtained the correlation between NSUN2 and immune cell infiltration through CIBERSORT algorithm and ESTIMATE method." (PMID 35978830, 2022). "In prostate cancer, the most common type of mutation in NSUN2 is amplification, and NSUN2 copy number variation is closely associated with NSUN2 expression and immune cell infiltration." (PMID 35978830, 2022). "In this regard, knockdown of Sphingosine kinase 1 (SK1) was associated with downregulation of NSUN2 in breast and prostate cancer cells, suggesting that pharmacological inhibitors of SK1 could potentially benefit cancers with overexpressed NSUN2." (PMID 32708015, 2020). "In prostate cancer, NSUN2 adds m5C modifications to TRIM28 mRNA, increasing its stability and promoting TRIM28 protein expression." (PMID 41256859, 2025). "The prostate cancer-specific transcription factor FOXA1 transcriptionally activates NSUN2 expression." (PMID 41256859, 2025). "NSUN2 expression is elevated in prostate cancer tissues and cells, where NSUN2 contributes to prostate cancer cell proliferation and migration." (PMID 41462962, 2025). "More importantly, the AR inhibitor enzalutamide can reduce NSUN2 expression and decrease the level of m5C modification in prostate cancer cells." (PMID 41413017, 2025). "In this way, a positive feedback loop is formed between NSUN2 and AR to promote the progression of prostate cancer." (PMID 41413017, 2025). "Strikingly, treatment with enzalutamide, an effective AR inhibitor, reduces NSUN2 expression and decreases the m5C modification level in prostate cancer cells." (PMID 36169095, 2022). "NSUN2 stabilizes AR mRNA through cluster 5‐methylcytosine modification and activates a positive feedback loop to promote prostate cancer." (PMID 36169095, 2022). "We determined the expression of NSUN2 through qPCR and western blot in a prostate normal epithelial cell line and four prostate cancer cell lines." (PMID 35978830, 2022). "In conclusion, we showed the gene expression profile of NSUN members and identify NSUN2, a core gene for m5C modification, as a potential biomarker for predicting prostate cancer prognosis." (PMID 35978830, 2022). "NSUN2 is highly expressed in prostate cancer, which contributes to the progression of prostate cancer, and is closely implicated in immune cell infiltration and chemotherapy drugs." (PMID 35978830, 2022). "In prostate cancer cell lines SK1 knockdown (KD) has significantly changed expression of several genes including downregulation of NSUN2, G3BP2 and upregulation of ETS1." (PMID 30971929, 2019). "High NSUN2 expression lowers the sensitivity of fluorouracil in prostate cancer." (PMID 38468490, 2024). "In addition, we analyzed the expression of NSUN2 in prostate cancer tissues and normal tissues by qPCR and immunohistochemistry, the expression of NSUN2 was elevated in prostate cancer." (PMID 35978830, 2022). "NSUN2 is expected to be a prospective marker and a new treatment target for prostate cancer." (PMID 35978830, 2022). "Furthermore, we also demonstrated that NSUN2 promotes the proliferation and migration of prostate cancer cells." (PMID 35978830, 2022).
prostate carcinoma (continued). "More importantly, we found significant differences in several important tumors signaling pathways, mTOR signaling pathway, HIPPO signaling pathway, MAPK signaling pathway, and Ras signaling pathway, which suggests that NSUN2 does have an impact on the development and progression of prostate cancer." (PMID 35978830, 2022). "Finally, we verified the expression of NSUN2 in prostate cancer cell lines and confirmed the role of NSUN2 on the biological behavior of prostate cancer cells by proliferation and migration-related assays." (PMID 35978830, 2022). "For instance, NSUN2 has been identified as a marker and novel target for nasopharyngeal carcinoma (NPC) and prostate cancer (PCa)." (PMID 41413017, 2025). "Apart from U87 cells, the effects of NSun2 intervention on ATX expression were also confirmed in colon cancer cells Colo320 and prostate cancer cells DU145." (PMID 33093178, 2020). "Then we analyzed the immune-related score for each prostate cancer case by ESTIMATE and found that NSUN2 had the highest correlation coefficient with the immune score and tumor purity, so we suggested that NSUN2 might be a key gene in prostate cancer and explored it further in-depth subsequently." (PMID 35978830, 2022).
nasopharyngeal carcinoma (12 papers, 2022 to 2026). A carcinoma arising from the nasopharyngeal epithelium. "NSUN2 was upregulated in nasopharyngeal carcinoma and predicted poor prognosis in a Gene Expression Omnibus (GEO) dataset and tissue microarray containing 125 cancer tissues." (PMID 41462962, 2025). "NSUN2 promoted nasopharyngeal carcinoma cell proliferation, migration, and invasion in vitro." (PMID 41462962, 2025). "NSUN2 can also regulate immune infiltration in nasopharyngeal carcinoma, which reveals that NSUN2 may act on immune cells to play a role in tumor progression." (PMID 37769000, 2023). "In nasopharyngeal carcinoma (NPC), NSUN2 overexpression correlates closely with poor patient prognosis." (PMID 41256859, 2025). "Furthermore, NSUN2 negatively regulates immune cell infiltration in the nasopharyngeal carcinoma (NPC) tumor microenvironment, suggesting that NSUN2 may be inversely related to sensitivity to immunotherapy and chemotherapy." (PMID 40370440, 2025). "Furthermore, NSUN2 was negatively correlated with the infiltration of immune cells in the nasopharyngeal carcinoma tumour microenvironment, suggesting that high expression of NSUN2 may reduce the sensitivity to immunotherapy." (PMID 38572667, 2024). "In nasopharyngeal carcinoma (NPC) specifically, NSUN2 negatively regulates immune cell infiltration in the TME." (PMID 37325635, 2023).